IQCM (IQ motif containing M)
Gene: Protein-coding gene on chromosome 4 (149,351,709 to 149,896,233, reverse strand). Ensembl gene ENSG00000234828.
Genetic constraint (gnomAD): Loss-of-function variants: 18 observed, 19.61 expected, observed/expected ratio (o/e) 0.92, 90% interval 0.63 to 1.36. The upper end of that interval is the gene's LOEUF score, 1.36, which puts it in group 5 of 6, group 1 being the genes least tolerant of losing a copy. Missense variants: 195 observed, 215.07 expected, observed/expected ratio (o/e) 0.91, 90% interval 0.81 to 1.02. Synonymous variants: 65 observed, 69.86 expected, observed/expected ratio (o/e) 0.93, 90% interval 0.76 to 1.14.
Homologues: Orthologues: chimpanzee IQCM (99% identical), macaque IQCM (91% identical), pig IQCM (67% identical), dog IQCM (64% identical), rabbit IQCM (64% identical), mouse Iqcm (59% identical), guinea pig IQCM (55% identical).
Diseases named in the same sentence as IQCM in open-access papers:
IQCM is named in the same sentence as 1 disease in open-access papers, as found by Europe PMC text mining. Sharing a sentence is not in itself a finding about the gene and the disease.
IQCM shares sentences with these, for which no sentence is quoted: cancer (1 paper).